IL25 (interleukin 25)
Diseases named in the same sentence as IL25 in open-access papers (continued):
Sharing a sentence is not in itself a finding about the gene and the disease.
inflammation (continued). "To further determine whether intra-epithelial Shp2 functioned on OVA-induced airway inflammation, we examined the levels of epithelium-derived cytokines IL-25 and IL-33 in the lung tissue of OVA-sensitized Shp2-deficient or control mice 24 hours after OVA inhalation." (PMID 28481957, 2017). "Initially, we utilized an IL-33-based model of AHR because both IL-33 and IL-25 have been previously shown to induce ILC2-mediated AHR and lung inflammation, although IL-33 is more potent than IL-2522." (PMID 33953190, 2021). "Recent studies have highlighted an important role of epithelial cytokines, including IL-25, IL-33 and TSLP, in lung inflammation." (PMID 34970267, 2021). "Besides, the correlations between BIRC3 expression and asthmatic eosinophilic/allergic inflammation indicators (FeNO, IgE, and EOS%), pulmonary function (FEV1, FEV1% pred, FVC% pred, and FEV1/FVC), and inflammatory cytokines (IL-4, IL-5, IL-13, IL-25, IL-10, IL-33, and TSLP) were analyzed." (PMID 35287655, 2022). "Herein, we hypothesize that in addition to mediate allergic airway inflammation and remodeling, epithelium‐derived triple cytokines, IL‐25/IL‐33/TSLP, can also potentiate non‐atopic lung parenchymal inflammation and fibrogenesis mainly by initiating and propagating type 2 immunity." (PMID 36082495, 2022). "Importantly, both IL-33 and IL-25 could activate ILC2, leading to production of IL-5 and IL-13, which mediates lung inflammation." (PMID 34970267, 2021). "However, whether IL‐25/IL‐17BR axis is involved in the pathogenesis of non‐atopic lung inflammation and fibrosis (especially IPF) is still not fully explored." (PMID 36082495, 2022). "On the other hand, only IL-33, but not IL-25 or TSLP, was important for induction of HDM-induced airway inflammation in mice sensitized “intranasally” with HDM35,36." (PMID 30082755, 2018). "On the other hand, IL-33, but not IL-25 or TSLP, was found to be important for development of HDM-induced “chronic” airway inflammation in mice." (PMID 24205109, 2013). "However, IL-33, but not IL-25 or TSLP, was shown to be responsible for development of airway inflammation in mice sensitized “intranasally” with house dust mite antigens." (PMID 26230091, 2015).
bacterial infections (7 papers, 2015 to 2024). "For bacterial infections, IL-25 had been reported to reduce the host mortality and tissue pathology in C. difficile infection; IL-25 had been reported to support the host defense against Staphylococcus aureus (S. aureus) via modulating the immunity." (PMID 39261649, 2024). "In summary, for bacterial infectious diseases, IL-25 is involved in the regulation of adaptive immunity and anti-inflammatory effect and influences the homeostasis of the intestinal immune through Th2 cells." (PMID 36119076, 2022). "Numerous studies illustrated that the expression of IL-25 is regulated by multiple pathogens, including parasitic, viral, and bacterial infections." (PMID 36119076, 2022). "However, IL-17A and IL-17F, which share IL-17RA with IL-25, play major roles in the host against bacterial infections." (PMID 36119076, 2022). "IL-25 was also found to have protective capabilities in an ex vivo enteroinvasion challenge model where exogenous IL-25 restored intestinal barrier functions and prevented bacterial infections." (PMID 36311787, 2022). "It has reported that IL-25 is up-regulated during some parasitic, viral, and bacterial infections." (PMID 36119076, 2022). "Furthermore, for brush cells in the small intestine it has recently been shown that they trigger IL-25-mediated type 2 immune responses upon a parasite and bacterial infection." (PMID 32116750, 2020). "However, IL-25’s role during bacterial infection has remained, until now, unexplored." (PMID 34449811, 2021).
cardiovascular disease (4 papers, 2015 to 2025). "Therefore, if similar athero-protective immunity by IL-25 can be induced in humans, it would represent a possible novel therapeutic approach for prevention and treatment of cardiovascular disease." (PMID 25629516, 2015).
metabolic disorders (3 papers, 2021 to 2026). "Whether IL-25 is also involved in the biogenesis of brown-in-white (brite)/beige adipocytes and associated metabolic disorders is not known." (PMID 34351905, 2021).
kidney (2 papers, 2021 to 2024). "In turn, IL-4/IL-13-induced AAM upregulate Ear11 production and inducing IL-25-dependent lung neutrophilia." (PMID 32457448, 2021).
digestive system diseases (1 paper, 2024). "Elevated levels of IL25 in the Central region may be associated with a higher incidence of skin diseases and circulatory diseases, and its decreased levels in Yakutia—with digestive system diseases, which are highly prevalent among the native Yakutia population." (PMID 39769502, 2024).
infectious disease (1 paper, 2022). A disorder directly resulting from the presence and activity of a microbial, viral, or parasitic agent in humans. "However, the mechanisms of IL-25 associated with infectious diseases call for an urgent need to investigate." (PMID 36119076, 2022). "Thus, in this review, we aim to briefly summarize the recent research progress on the functions of IL-25 in infectious diseases and probe into the potential therapeutic effects." (PMID 36119076, 2022). "Thus, further investigations are necessary to explore the different mechanisms induced by IL-25 expression in different infectious diseases." (PMID 36119076, 2022). "IL-25 is a cytokine with a dual function in infectious diseases." (PMID 36119076, 2022). "Therefore, it’s feasible to use IL-25 as a novel therapeutic target for infectious diseases." (PMID 36119076, 2022). "Notably, the biofunction of IL-25 in infectious diseases is still unclear." (PMID 36119076, 2022). "Thus, the current review will shed light on the pivotal roles of IL-25 in infectious diseases." (PMID 36119076, 2022). "However, the precise roles of IL-25 in infectious diseases remain largely unknown." (PMID 36119076, 2022).
kidney disease (1 paper, 2024). "According to several previous reports, IL-25 protects against renal injury in individuals with drug-induced kidney disease by inducing M2 macrophages or eliciting group 2 innate lymphoid cells and multipotent progenitor type 2 cells." (PMID 38785317, 2024). "IL-25 regulates inflammation by modulating type 2 immune responses, but the mechanism by which IL-25 affects kidney disease remains unclear." (PMID 38785317, 2024).
IL25 also shares sentences with these, for which no sentence is quoted: Allergy (33 papers); chronic rhinosinusitis (6); fibrosis (5); diabetes (4); respiratory diseases (4); adenocarcinoma (3); chronic obstructive pulmonary disease (3); chronic rhinosinusitis with nasal polyps (3); Cirrhosis (3); pancreatic cancer (3); Acute hepatitis (2); cystic fibrosis (2); lung mucoepidermoid carcinoma (2); malaria (2); sarcoidosis (2); trauma (2); abortion (1); abscesses (1); Acute hepatic failure (1); alcoholic liver diseases (1); anaphylaxis (1); astrocytoma (1); autoimmune gastritis (1); bladder tumor (1); Brain atrophy (1); bronchiolitis (1); Chronic colitis (1); chronic hepatitis C (1); chronic rhinosinusitis without nasal polyps (1); clostridium difficile infection (1).
A further 34 diseases each share a sentence with IL25 in 1 paper.